TSPAN10 (tetraspanin 10)
Description:
Part of TspanC8 subgroup, composed of 6 members that interact with the transmembrane metalloprotease ADAM10. This interaction is required for ADAM10 exit from the endoplasmic reticulum and for enzymatic maturation and trafficking to the cell surface as well as substrate specificity. Different TspanC8/ADAM10 complexes have distinct substrates.
Synonyms: OCSP
Gene: Protein-coding gene on chromosome 17 (81,637,171 to 81,648,754, forward strand). Ensembl gene ENSG00000182612.
Subcellular location: Cell membrane
Genetic constraint (gnomAD): Loss-of-function variants: 11 observed, 12.48 expected, observed/expected ratio (o/e) 0.88, 90% interval 0.55 to 1.45. The synonymous counts are far from expectation, so gnomAD's model fits this gene poorly and the ratio says little. Missense variants: 486 observed, 404.55 expected, observed/expected ratio (o/e) 1.2, 90% interval 1.12 to 1.29. Synonymous variants: 241 observed, 190.7 expected, observed/expected ratio (o/e) 1.26, 90% interval 1.14 to 1.41.
Homologues: Orthologues: guinea pig TSPAN10 (67% identical), pig TSPAN10 (62% identical), dog TSPAN10 (61% identical), chimpanzee TSPAN10 (60% identical), rat Tspan10 (60% identical), mouse Tspan10 (59% identical), macaque TSPAN10 (54% identical), tropical clawed frog tspan10 (34% identical), zebrafish tspan10 (32% identical). Paralogues in human: CD37 (20% identical), TSPAN17 (19% identical), TSPAN5 (19% identical), ROM1 (19% identical), TSPAN14 (19% identical), TSPAN33 (19% identical), CD82 (18% identical), TSPAN15 (17% identical), CD151 (16% identical), TSPAN11 (16% identical), TSPAN1 (15% identical), TSPAN4 (15% identical), and 20 more.
Diseases named in the same sentence as TSPAN10 in open-access papers:
TSPAN10 is named in the same sentence as 18 diseases in open-access papers, as found by Europe PMC text mining. Sharing a sentence is not in itself a finding about the gene and the disease. The quoted sentences say what the papers report.
Strabismus (7 papers, 2019 to 2024). A misalignment of the eyes so that the visual axes deviate from bifoveal fixation. "In cerebellum and human cerebellar hemisphere the strabismus-associated risk allele was strongly associated with reduced expression of TSPAN10 (p = 1.30E−10 and p = 8.10E−12, respectively) consistent with degradation of an mRNA isoform via NMD." (PMID 31073882, 2019). "Thus, in summary, there was strong evidence that the causal variant underlying the association with strabismus acts as a cis-eQTL for TSPAN10 in neural tissue, and for PDE6G and ARL16 in certain other tissues." (PMID 31073882, 2019). "These variants were associated with reduced TSPAN10 gene expression in brain tissues, although such eQTL effects were also observed for the adjacent genes PDE6G and ARL16, suggesting that the risk of strabismus could be mediated through any one or more of these genes." (PMID 31073882, 2019). "Notably, the lead variant at the strabismus locus, rs75078292, is in very tight LD (r2 = 0.98) with non-synonymous variant rs6420484, which introduces a tyrosine residue in place of an evolutionarily conserved cysteine at position 177 of TSPAN10, the gene encoding tetraspanin-10 (Online Resource 4)." (PMID 31073882, 2019).
myopia (4 papers, 2018 to 2025). "We examined the top 64 myopia-associated loci that were expressed in the retinal layers and associated with common refractive errors, SNPs representing TSPAN10, KCNJ5, TFAP2B, and FBN2 had |nSL|> 2, which were under strong selection." (PMID 37919796, 2023). "In contrast, selection favoring the risk allele associated with myopia predisposition was only observed in TSPAN10 and FBN2 (P = 8.63 × 10−11 for rs6860901)." (PMID 37919796, 2023). "Other suggestive signals were located near loci previously associated with retinal features, myopia, or abnormality of refraction, such as the TSPAN10/NPLOC4/PDE6G locus or the retinoid acid receptor beta RARB, associated with retinal vasculature in a previous GWAS." (PMID 38365752, 2024). "Given its significant association with hair color and myopia and the selection favoring myopia at this locus, we inferred that the selective pressure at TSPAN10 may originate from adaptation events related to the light environment rather than myopia." (PMID 37919796, 2023). "Ocular expression of TSPAN10 has been identified in the iris, ciliary body and retinal pigment epithelium and this locus has previously demonstrated genome-wide significant association with eye colour, myopia and age-related macular degeneration." (PMID 30306274, 2018). "We identified significant selection signatures in myopia-associated genes related to sunlight, including RHO, TSPAN10, and MED1, and we validated the interaction between these genes and the light environment." (PMID 37919796, 2023). "We proposed TSPAN10 as evidence of evolutionary mismatch in myopia." (PMID 37919796, 2023). "Therefore, selective signatures in RHO and TSPAN10 may result from sunlight-related environmental factors, such as pigmentation, rather than selective pressure on myopia." (PMID 37919796, 2023).
albinism (2 papers, 2024 to 2025). A congenital disorder characterized by partial or complete absence of melanin pigment in the eyes, hair, or skin. "Many of these loci encompass variants previously linked to retinal layer thickness parameters (including TSPAN10 and LINC00461) while a subset of them has been linked to monogenic disorders, most notably, albinism (including TYR, OCA2 and GPR143)." (PMID 40666342, 2025).
Astigmatism (1 paper, 2018). A type of refraction error associated with abnormal curvatures on the anterior and/or posterior surface of the cornea. "The identification of 3 genes (HERC2, OCA2 and TSPAN10) associated with eye colour and astigmatism implies that certain eye colour(s) may confer susceptibility to astigmatism or that these eye colour-related genes have distinct, pleiotropic actions that lead to astigmatism." (PMID 30306274, 2018). "Three of these loci also demonstrated genome-wide significant association with refractive astigmatism: LINC00340, HERC2/OCA2 and NPLOC4/TSPAN10." (PMID 30306274, 2018). "For refractive astigmatism, markers achieving genome-wide significant association clustered in three regions: LINC00340, (top marker: rs12196123, P = 1.60 × 10−15), HERC2 (top marker: rs1129038, P = 2.30 × 10−11) and TSPAN10/NPLOC4 (top marker: rs34635363, P = 2.00 × 10−9)." (PMID 30306274, 2018).
Corneal astigmatism (1 paper, 2018). "Single marker-based association tests for corneal astigmatism identified four genome-wide significant loci (P < 5 × 10−8) near the genes ZC3H11B (1q41), LINC00340 (6p22.3), HERC2/OCA2 (15q13.1) and NPLOC4/TSPAN10 (17q25.3)." (PMID 30306274, 2018).
melanoma (1 paper, 2012). A malignant, usually aggressive tumor composed of atypical, neoplastic melanocytes. "Transwell migration assays showed that down-regulating Hyal1, Tspan10, and Mc1r resulted in clearly reduced migration of the melanoma cells." (PMID 22363655, 2012). "Thus, it would not be surprising if Tspan10 partakes in regulating migration of melanoma as shown in our study although detailed mechanisms need further analyses." (PMID 22363655, 2012).
metastatic melanoma (1 paper, 2018). A melanoma that has spread from its primary site to another anatomic site. "Moreover, single nucleotide variations in exonic region of TSPAN10 were detected in metastatic melanoma." (PMID 29650964, 2018).
TSPAN10 also shares sentences with these, for which no sentence is quoted: cancer (2 papers); age-related macular degeneration (1); amblyopia (1); colon carcinoma (1); congenital stationary night blindness (1); Esotropia (1); hyperopia (1); non-small cell lung carcinoma (1); retinal disorder (1); Retinal dystrophy (1); tumor (1).